CDA (cytidine deaminase)
Diseases named in the same sentence as CDA in open-access papers (continued):
Sharing a sentence is not in itself a finding about the gene and the disease.
cancer (continued). "First, they reduced the number of CD8+ T cells in mice with sgNT and sgCda tumors receiving anti-PD-1 treatment and discovered that the CDA-depleted cancer cells had lost their ability to attract macrophages and maintain their immunosuppressive phenotype." (PMID 40011298, 2025). "CDA is an enzyme that hydrolytically deaminates cytidine to uridine and deoxyuridine, preventing DNA integration in cancer cells." (PMID 40011298, 2025). "Studies have revealed that the pathway enzyme cytidine deaminase (CDA) in cancer cells contributes to the production of uridine diphosphate (UDP)." (PMID 39852139, 2025). "Most importantly, CDA targeting in PDAC cancer cells alters the TME, allowing T cells to respond to anti-PD-1." (PMID 40011298, 2025). "CDA contributes to chemoresistance in cancer treatment, but its role in maintaining the extracellular nucleotide pool and immunotherapy resistance remains unexplored." (PMID 40011298, 2025). "In individuals with PDAC, high CDA levels in cancer cells correlate with increased TAMs, lower cytotoxic T cells and possibly anti-PD-1 resistance." (PMID 38844817, 2024). "We aimed to build upon these correlations with analysis of cytidine deaminase function in cancer by interrogating this protein family for yet to be discovered cellular roles." (PMID 38976757, 2024). "Studies have shown that the activity of the CDA enzyme can be a predictive biomarker in gemcitabine-treated cancer patients." (PMID 38375040, 2024). "From the top ten ranked candidates, we focused on CDA because nothing is known on pyrimidine metabolism in cancer immunotherapy." (PMID 38844817, 2024). "Gemcitabine inactivation is facilitated by cytidine deaminase (CDA) which converts gemcitabine to 2′,2′-difluorodeoxyuridine and cancer patients with lower serum levels of CDA show a significantly longer survival than patients with high CDA levels." (PMID 38744194, 2024). "Mycoplasma hyorhinis confers chemoresistance to cancer cells by metabolizing gemcitabine into its inactive metabolite, 2′,2′-difluorodeoxyuridine, through its cytidine deaminase (CDD) activity." (PMID 39360320, 2024). "As a result, targeting CDA in cancer cells or inhibiting P2Y6 in macrophages renders T cells susceptible to anti-PD-1 therapy." (PMID 38844817, 2024). "To date, APOBEC3A is emerging as the more prominent cytidine deaminase that edits the genome in cancer." (PMID 38976757, 2024). "METTL14 is upregulated in gemcitabine‐resistant cancer cells which increases the expression of gemcitabine metabolizing enzyme cytidine deaminase (CDA)." (PMID 39661414, 2024). "We did not observe any additional effect of CDZ when treating sgCda tumors, suggesting that the phenotype is due to CDA inhibition in cancer cells only." (PMID 38844817, 2024). "Together, CDA induction in cancer cells and its correlation with ICB resistance suggest its possible role in hampering antitumor responses and immunotherapy efficacy." (PMID 38844817, 2024). "This study links both processes by showing that cytidine deaminase APOBEC3A, a source of cancer-initiating mutations, also contributes to cancer progression by promoting ribosome biogenesis." (PMID 38976757, 2024). "Even so, APOBEC3A’s newfound function in ribosome biogenesis emphasizes it as a top candidate cytidine deaminase target for cancer therapeutics." (PMID 38976757, 2024). "In terms of the extracted mutational signatures, a previous study revealed that the APOBEC cytidine deaminase signature was significant in 14 other cancer types." (PMID 38486026, 2024). "Blocking cytidine deaminase supported degradation of the DNMT1 protein in cancer cell lines (range 82–90%), even though decitabine treatment alone of cancer cells caused a small but significant increase in DNMT1 mRNA expression." (PMID 37208732, 2023). "The study presents CDA manipulation as a promising strategy for cancer therapy; however, greater research is warranted to better understand the role of CDA in oncogenesis." (PMID 37796556, 2023).
cancer (continued). "Intriguingly, TAMs can modulate therapy resistance by upregulating CDA in cancer cells and by releasing pyrimidine nucleoside deoxycytidine that competes with GEM and lowers its active dose." (PMID 37444617, 2023). "For instance, the dislodging of miR-365 shed from MDEs abolished GEM efficacy through the upregulation of the triphosphonucleotide pool and the induction of CDA in cancer cells." (PMID 37444617, 2023). "Certain cancer cells rely on the salvage enzymes cytidine deaminase (CDA) and dCMP deaminase (DCTD) to inactivate these cytidine derivative drugs by deamination." (PMID 37378658, 2023). "As most cancer cells lack the carboxylesterase and cytidine deaminase necessary to convert CAP to 5’-deoxy’5-fluorouridine (DFUR), MC38 cells were treated with the combination of HQ and DFUR." (PMID 37337282, 2023). "In cancer genomes, these regions are a perfect substrate for hypermutation by ssDNA specific APOBEC cytidine deaminase(s) leaving a permanent record of mutation clusters highly enriched with the APOBEC hypermutation signature." (PMID 36919609, 2023). "CDA is frequently overexpressed in many cancers, including pancreatic, stomach, testicular, and vaginal cancer." (PMID 35999456, 2022). "DMDC is resistant to metabolism by cytidine deaminase and was proven effective in xenograft models of cancers, where cytidine deaminase activity is high and gemcitabine response is typically low." (PMID 35740940, 2022). "Cell lines from several cancer types consistently express low levels of CDA and there is a large proportion of cell lines from different cancer types with poor expression of this enzyme." (PMID 36424385, 2022). "This suggested that in the presence of a DHODHi, an excess of cytidine would be deleterious for low CDA expressing cancer cell lines." (PMID 36424385, 2022). "We have shown that cytidine deaminase (CDA) expression is downregulated in about 60% of cancer cells and tissues." (PMID 35925417, 2022). "We recently identified CDA as a new player in the maintenance of genome stability and reported that CDA expression was lost or significantly reduced in about 60% of cancers affecting the general population." (PMID 35982128, 2022). "Only the addition of 5′-DFCR during the recovery phase, e.g., once CDA expression levels have increased, further augmented the anti-cancer effect compared to MTA and cisplatin combination therapy alone." (PMID 33874986, 2021). "In agreement, an extensive in silico analysis revealed that CDA expression is downregulated in about 60% of cancer cell lines and tissues and that the low CDA expression levels correlate with CDA promoter methylation." (PMID 33874986, 2021). "CDA expression is epigenetically silenced in approximately 60% of cancer cell lines and tissue specimen." (PMID 33874986, 2021). "Nevertheless, our analysis reveals the existence of a subgroup of patients in whom CDA expression in cancer cells increases dramatically after chemotherapy." (PMID 33874986, 2021). "In summary, the changes in CDA expression levels induced by chemotherapy vary significantly between cancer patients." (PMID 33874986, 2021). "The cytidine deaminase, APOBEC3A (A3A), is a prominent source of mutations in multiple cancer types." (PMID 34697369, 2021). "The upregulation of the triphosphonucleotide pool in cancer cells and the induction of the enzyme cytidine deaminase were two major changes in this case." (PMID 33869017, 2021). "APOBEC3A is a cytidine deaminase driving mutagenesis, DNA replication stress and DNA damage in cancer cells." (PMID 32532990, 2020). "The determination of CDA expression status within cancer cells and tissues is opening up new possibilities for cancer treatment." (PMID 32807821, 2020). "CDA is released from the cell and is found in the serum; CDA has been detected in patients with several cancer types and correlates with responses to chemotherapy." (PMID 35582220, 2020).
cancer (continued). "In consideration of the essential roles of AID/APOBEC cytidine deaminase in cancer evolution and immune activation, we focused our insights on the AID/APOBECs in HNSC." (PMID 32775421, 2020). "Overexpression of ARRB2 induced expression of ENT1, which promotes influx of Gemcitabine into cancer cells, and was also shown to inhibit conversion of gemcitabine into inactive metabolites by inhibiting the enzyme Cytidine Deaminase (CDA)." (PMID 33297302, 2020). "Capecitabine is selectively converted to 5-FU in cancers via a cascade of three enzymes: carboxyl esterase, cytidine deaminase, and TP10." (PMID 32066801, 2020). "We have shown that CDA expression is downregulated in about 60% of cancer cells and tissues, mostly due to DNA methylation." (PMID 32807821, 2020). "A previous study revealed that high expression of CDA was responsible for cytidine resistance in cancer cells." (PMID 30002603, 2018). "DNMTIs such as 5-aza are subject to rapid degradation by hydrolytic cleavage and deamination by cytidine deaminase and are unstable after intravenous infusion, limiting their potential as cancer therapeutics." (PMID 27936464, 2017). "We did this by in silico analyses of MAPT and CDA expression levels in several cohorts of cancer cell lines and tissues." (PMID 28947735, 2017). "The expression of APOBEC3A or CDA positively correlated the most with C>U RNA editing in cancer tissues, MEPs or macrophages." (PMID 25898173, 2015). "Here, another mechanism of resistance was demonstrated: protection for otherwise treatment-sensitive cancer cells within a tissue environment that expresses high levels of CDA." (PMID 23087155, 2012). "We document for the first time that sanctuary in an organ which expresses high levels of the enzyme cytidine deaminase (CDA) is a mechanism of cancer cell resistance to cytidine analogues." (PMID 23087155, 2012). "CDA is a prominent enzyme in the catabolism of cytosine nucleoside analogues, and is often over-expressed in cancer cells that have acquired resistance to those analogues." (PMID 22616006, 2012). "The release of UTP and UDP by cancer cells has been hypothesized to be a determinant factor in CDA-dependent resistance to anti-PD-1 therapy, as CDA is engaged in a pathway leading to the synthesis and release of uracil nucleotides in cancer cells." (PMID 40011298, 2025). "Moreover, CDA expression was minimal in macrophages and mostly observed in endothelial and cancer cells." (PMID 40011298, 2025). "By activating P2Y6 receptors in TAMs, CDA induction in cancer cells encourages immunosuppression." (PMID 40011298, 2025). "Additionally, CDA reduction in cancer cells made tumors more sensitive to immunotherapy, presumably by overcoming immunosuppressive TAMs and forcing them to adopt an immunostimulatory phenotype." (PMID 40011298, 2025). "Through systematic evaluation of cfDNA fragmentation patterns, it was found that these regions were significantly enriched for cancer-related functional ontologies, such as the estrogen signaling pathway, Rab GTPase binding, lipid metabolic processes, and cytidine deaminase activity." (PMID 40298367, 2025). "Thus, CDA inhibition in cancer cells breaks immunosuppression and enables T cell response to anti-PD-1." (PMID 38844817, 2024). "Therefore, CDA induction in cancer cells promotes immunosuppression through activation of P2Y6 in TAMs." (PMID 38844817, 2024). "Since this does not provide any evidence for a functional role within the context of tumorigenesis or cancer progression, we sought to examine any correlations between cytidine deaminase expression and patient survival across cancer type using the associated patient survival data." (PMID 38976757, 2024). "We show that CDA in cancer cells contributes to the uridine diphosphate (UDP) pool." (PMID 38844817, 2024). "Taken together, CDA is enriched in the cancer epithelial compartment in both humans and mice." (PMID 38844817, 2024).
cancer (continued). "Conversely, low CDA expression in cancer cells identifies a subgroup of individuals with PDAC with fewer immunosuppressive TAMs and more T cells who might benefit from ICB." (PMID 38844817, 2024). "Additionally, we investigated the effects of decitabine and/or PBA on programmed cell death and studied the regulation of caspase 3 & 7, PARP and PPARγ after daily treatment of the cancer cell lines for 72 h and in CDA gene knockdown cell lines." (PMID 37208732, 2023). "Moreover, both APOBEC3A and APOBEC3B display cytidine-deaminase-independent roles in carcinogenesis that add complexity when it comes to comprehending their roles in cancer." (PMID 36980505, 2023). "Nevertheless, high CDA expression is only found in a few cancer types, which could limit the application of 5hmdC and 5fdC in cancer treatment." (PMID 37378658, 2023). "In addition, PC‐D, the second patient with elevated TMB, exhibited SBS2 and SBS13, which are attributed to APOBEC cytidine deaminase activity and account for more than one‐third of human cancers signatures." (PMID 36808802, 2023). "In addition, IL-13 promotes the biosynthesis of cytidine deaminase in colonic epithelial cells, conferring the potential to activate the inflammatory-cancer transition in the intestine." (PMID 37534250, 2023). "Therefore, it appears that CDA has the potential to promote cancer cell survival in the presence of anticancer drugs." (PMID 35999456, 2022). "They showed that therapeutically targeting the metabolism of this key enzyme led to the selective depletion of CDA-expressing cancer cells, a strategy that, if successful clinically, could help patients to overcome resistance to ALK-inhibiting drugs." (PMID 35999456, 2022). "If the positive effect of cytidine on cancer cells expressing high-CDA and T cells is due to their CDA activity, it would be expected that the small molecule inhibitor of CDA tetrahydrouridine (THU) would prevent the rescue by cytidine of these cells from the DHODHi treatment." (PMID 36424385, 2022). "Therefore, potent inhibitors of human cytidine deaminase such as 1-beta-ribofuranosyl-1,3-diazepinone are potential treatment strategies in cancer patients as small molecule therapeutic adjuvants." (PMID 35684435, 2022). "Altogether, targeting extracellular CDA, and perhaps other enzymes that accumulate in plasma may contribute to improve cancer treatment." (PMID 36424385, 2022). "We then addressed the question as to whether the increase in CDA activity and mRNA levels in BC patients was due to the disease or cancer treatment." (PMID 35982128, 2022). "However, many cancers resist to GEM and the main involved mechanism consists of an up-regulation of the catabolic enzyme Cytidine Deaminase (CDA), deficiency in the anabolism enzyme Deoxycytidine Kinase (DCK), and alterations in nucleoside influx transporters." (PMID 36059648, 2022). "In CDA-overexpressing cancer cells, however, 5hmdC and 5fdC can be deaminated to yield 5hmdU and 5fdU, respectively, which can be incorporated into DNA, leading to cell cycle arrest and/or accumulation of cytotoxic double-stranded DNA breaks that cause cell death." (PMID 35999456, 2022). "The mRNA sequence assayed is specific for the product of the cancer cell’s CDA gene." (PMID 34830914, 2021). "Moreover, severe cellular gemcitabine toxicity has been observed in cancer patients with low activity of CDA." (PMID 34777634, 2021). "APOBEC3B has cytidine deaminase activity against ssDNA, causing a series of GC to AT mutations, and can modify the genome in somatic cells in vitro and in high APOBEC3B-expressing cancer cells." (PMID 32880638, 2020). "The cytidine deaminase pattern is widespread in human cancers." (PMID 33141854, 2020). "Moreover, our findings for cancer tissues presenting concomitant cytidine deaminase underexpression and Tau upregulation open up new possibilities for anti-cancer treatment." (PMID 28947735, 2017).
cancer (continued). "Overall, our data indicate the existence of a causal link between the expression of the CDA and MAPT genes that could be exploited in the development of new anti-cancer strategies." (PMID 28947735, 2017). "APOBEC cytidine deaminase activity is a major source of hypermutation in cancer." (PMID 25401976, 2015). "Moreover, in both people and mice, CDA is abundant in the cancer epithelial compartment." (PMID 40011298, 2025). "Our findings provide structural insights into the molecular basis for recognizing gemcitabine metabolite by a bacteria CDA protein and may provide potential strategies to combat cancer drug resistance and improve the efficacy of gemcitabine-based chemotherapy in GBC treatment." (PMID 38492776, 2024). "A deamination step could thus be required for 5hmdC and 5fdC to kill CDA-null cancer cells." (PMID 37378658, 2023). "Furthermore, we investigated cell proliferation of cancer cell lines following CDA gene knockdown." (PMID 37208732, 2023). "The cytidine deaminase, Apolipoprotein B mRNA editing enzyme catalytic subunit 3B (APOBEC3B, herein termed A3B), is a critical mutation driver that induces genomic instability in cancer by catalyzing cytosine-to-thymine (C-to-T) conversion and promoting replication stress (RS)." (PMID 37270643, 2023). "Thus, increased CDA expression might augment cancer cell survival via the protective effect of (deoxy)uridine." (PMID 33874986, 2021). "However, little evidence for transcriptional asymmetry of APOBEC-induced mutations in cancer genomes exists, indicating that ssDNA within transcription bubbles may be protected from APOBEC cytidine deaminase activity." (PMID 34697369, 2021). "However, the cytidine deaminase activity of APOBEC3 enzymes also induces somatic mutations in host genomes, which may drive cancer progression." (PMID 28825669, 2017). "To corroborate the mechanistic findings in human datasets, we aimed to reveal the link between CDA expression and the immune landscape in PDAC and many other cancers." (PMID 38844817, 2024). "Currently, cytidine deaminase inhibitors are being developed, including against APOBEC3A, with a focus on their application in cancer therapy." (PMID 38976757, 2024). "THU inhibits CDA activity, and the combined THU and decitabine treatment of cancer cells was similarly effective in inhibiting JAK1." (PMID 37208732, 2023). "Cytidine deaminase (CDD), an important metabolic enzyme involved in drug resistance development in cancer cells, is derived from cancer cells or bacteria within cancer cells." (PMID 36797231, 2023). "Altogether, this study indicates that reducing extracellular CDA activity (CDA is not only present inside cells but also in human plasma) may provide a means to increase the therapeutic index of DHODHi especially in patients with cancers where CDA expression is low." (PMID 36424385, 2022). "Consistently, the protein levels of pSTAT3, SOX2, CDA, and ABCC2 in cancer cells were decreased after silencing CAV1 in CAFs." (PMID 35045883, 2022). "Future studies will be required to dissect the details of the role played by CDA in the EMT and the survival of therapy-resistant cancer cells during targeted therapy." (PMID 35999456, 2022). "Consistently, the protein levels of pSTAT3, SOX2, CDA, and ABCC2 in cancer cells were increased after incubation with miR-660-3p-silenced CAFs, while miR-660-3p overexpression in CAFs reversed this effect." (PMID 35045883, 2022). "Our study also revealed the treatment-induced increase in CDA and TYMP expression is dependent on the chemotherapeutic drug, the treatment schedule and also on the genetic and EMT-status of the individual cancer cell." (PMID 33874986, 2021). "Cytidine deaminase (CDA), inside or outside of the cancer cell, will deaminate gemcitabine, altering transporter affinity." (PMID 34830914, 2021).